BRAF (B-Raf proto-oncogene, serine/threonine kinase)
Diseases named in the same sentence as BRAF in open-access papers (continued):
Sharing a sentence is not in itself a finding about the gene and the disease.
melanoma (continued). "HLA 1 is necessary for the presentation of antigens for recognition by T cells and, therefore, by reducing its expression, BRAF-mutant melanoma cells can escape recognition." (PMID 32645969, 2020). "Here, using single cell proteomic and metabolic data the authors uncover that isogenic BRAF mutant melanoma cells can take two distinct paths to become tolerant to BRAF inhibition." (PMID 32393797, 2020). "We have previously shown that melanoma cells resistant to BRAF-targeted therapy acquire NRP1 neo-expression, driving an intrinsic mechanism of drug refractoriness." (PMID 32784465, 2020). "Ultimately, we examined the role of A20 in the acquired resistance to Vemurafenib in BRAF-mutant melanoma." (PMID 32968045, 2020). "Herein, we reviewed the paradoxical fibro-mechanic reprogramming of BRAF-mutant melanomas, which is achieved in response to MAPK pathway inhibition." (PMID 32466585, 2020). "Anyway, the remarkable metabolic flexibility and reprogramming of melanoma cells account for the impressive aggressiveness of CM and can also sustain resistance response to BRAF/MEK inhibitors (BRAFi/MEKi) and immunotherapy." (PMID 32528879, 2020). "Two of the selected studies clearly demonstrated this; the use of THC in mice with induced BRAF/NRAS wild-type tumors promoted autophagy in melanoma cells." (PMID 32839414, 2020). "Here we show the genetic and phenotypic changes induced by treatment with programmed cell death-1 (PD-1) blockade in a genetically engineered mouse model of melanoma driven by oncogenic BRAF." (PMID 32051401, 2020). "In melanoma, combination BRAF and MEK inhibitors with an A2AR antagonist induces significant tumor control in preclinical studies." (PMID 32351498, 2020). "The aim of this study was therefore to assess treatment patterns and outcomes among patients with BRAF‐mutant advanced melanoma who initiated 1L treatment with aPD‐1 or BRAF/MEKi in a large network of community oncology clinics." (PMID 32871054, 2020). "The BRAF inhibitors vemurafenib, dabrafenib and encorafenib are used in the treatment of patients with BRAF-mutant melanoma." (PMID 32645969, 2020). "In BRAFV600E-mutant melanoma xenograft models the ERK inhibitor ulixertinib (BVD-523) showed impressive synergistic growth-inhibitory effects upon combination with BRAF inhibitors." (PMID 33255177, 2020). "In another study, BRAF V600E expressing malignant melanoma cells with resistance to RAF inhibitors showed activation of the EGFR/PI3K/AKT pathway." (PMID 32046099, 2020). "We have found a large diversity of transcript levels between three representative melanoma cell lines, and this was also observed when transcript levels of three selected genes were assessed in six cell lines of either the BRAF or NRAS subtype." (PMID 32466509, 2020). "BRAF V600E was found as the most common mutant position and had a strong connection with the morbidity and prognosis of melanoma." (PMID 33330635, 2020). "Based on melanoma studies, a patient with RRMM who had BRAF V600E mutation was treated with cobimetinib plus vemurafenib and achieved a rapid and lasting response." (PMID 33168044, 2020). "We also found that miR-125b-5p inhibitor abolish the role of LINC00520 siRNA on the EIF5A2 expression, proliferation and metastasis of BRAF-WT melanoma cells." (PMID 32466797, 2020). "Based on the presence of mutations in BRAF, RAS, or neurofibromatosis type 1 genes, the Cancer Genome Atlas Research (TCGA) network has recognized four geneticly distinct forms of melanoma." (PMID 33424993, 2020). "Recently, GRP78 was also implicated in the maintenance/reestablishment of MEK/ERK signaling in therapy-resistant BRAF mutant melanomas, and in maintaining stemness in pancreatic cancer cells in response to therapy-associated oxidative and protein stress." (PMID 33187540, 2020). "Immune resistance has been demonstrated in BRAF inhibitor-resistant melanoma cell lines with increased PD-L1 expression, which permitted host immune cell evasion." (PMID 32260561, 2020).
melanoma (continued). "This allows the repurposing of the BRAF V600E inhibitor vemurafenib from melanoma to colon cancer therapy." (PMID 33520715, 2020). "This was expected in the context of the molecular landscape of melanomas that can be divided into four distinct subclasses, including BRAF subtype and NRAS subtype." (PMID 32784823, 2020). "For example, it has recently been shown that aging fibroblasts secrete high levels of different lipids, including ceramides, which can promote melanoma resistance to BRAF and MEK inhibitors." (PMID 33291749, 2020). "In turn, this paradoxical upregulation had been linked to increased incidence in cutaneous SCCs that harbor RAS mutation, as well as reported cases of dysplastic nevi and wild-type BRAF melanomas, in patients after vemurafenib treatment." (PMID 32429485, 2020). "The most common mutation is the result of a substitution of glutamic acid for valine in codon 600 (BRAFV600E), which occurs in approximately 90% of BRAF-mutant melanomas." (PMID 32054078, 2020). "Activating HRAS mutations are found in approximately 20% of Spitzoid neoplasms, while BRAF and NRAS mutations are mostly found in conventional melanomas." (PMID 33100226, 2020). "Subpopulations expressing high levels of Met (Met-high) in melanoma cells show a varied phenotype, resistance to BRAF inhibitors, and increased lung metastasis." (PMID 33081785, 2020). "It was shown that small subpopulations of AXL-positive cells are present in untreated melanoma samples, as well as patient-derived xenografts (PDXs), implying that they can be positively selected in the presence of BRAF/MEK inhibitors." (PMID 33291749, 2020). "BRAF and NRAS were also the more frequently mutated genes in melanoma samples as described by others, except the TERT gene which was not included in the NGS panel." (PMID 33083132, 2020). "BRAF(V600E) mutation and its continuously activated downstream MEK1/2-ERK1/2 cascade are found in 50% of melanomas and are important for malanomagenesis." (PMID 33392197, 2020). "Macrophage-mediated resistance to BRAF inhibitors in melanoma was then reversed by blocking the MAPK pathway or macrophage-secreted VEGF." (PMID 32509781, 2020). "miR-204-5p and miR-211-5p are described to be upregulated by vemurafenib and both are stimulating MAPK pathways and also being involved in the emergence of melanoma cells resistance to BRAF inhibitor." (PMID 32555626, 2020). "After that, the patient's melanoma was confirmed to have the BRAF wild‐type gene and PD‐L1 expression was 80%." (PMID 32761808, 2020). "And lastly, secreted WNT5A (as opposed to WNT3A) has been shown to negatively regulate WNT/β-catenin signaling in several cancer types, including in a subgroup of melanoma patients exhibiting acquired resistance to BRAF-inhibition." (PMID 32238882, 2020). "Combining the RAF inhibitor vemurafenib with the glycolytic suppressor, dichloroacetate resensitized the vemurafenib-resistant melanoma cells to BRAF inhibition." (PMID 32046099, 2020). "Neurofibromin 1 (NF1) deficiency overcame BrafV600E-induced senescence and conferred BRAF inhibitor resistance in melanoma." (PMID 31285545, 2020). "Some of these include BRAF amplification, oncogenic NRAS mutations, and MEK1/2 mutations, in addition to a PAX3-mediated upregulation of MITF in approximately 80% of melanoma during early stages of resistance." (PMID 32517051, 2020). "While monotherapy with BRAF inhibitors shows good efficacy against BRAF-mutant melanomas, patients can easily develop resistance through upregulation of RTKs or NRAS." (PMID 32429485, 2020). "Available data support the synergy between these treatment approaches, indicating such combinations provide an additional beneficial effect on the tumour microenvironment and immune response in BRAF-mutant melanoma." (PMID 32645969, 2020).
melanoma (continued). "All together, those results indicated that the growth inhibitory effects of LNP4 is mediated by the simultaneous inhibition of Bcl-2 and VEGF-A oncogenes in BRAF-mutant melanoma cells." (PMID 32178301, 2020). "In this study, we demonstrate that in melanoma cells, BRAF inhibition curtails IFN‐γ‐induced PD‐L1 expression through two complementary mechanisms: decreased STAT1 activity and attenuation of protein translation." (PMID 32330348, 2020). "Altogether, these data support an MITF‐dependent role for the RANKL‐mediated increase in melanoma survival upon BRAF inhibition." (PMID 31323160, 2020). "The MAPK signaling pathway is highly active in advanced metastatic melanomas, particularly through the BRAF pathway." (PMID 32358995, 2020). "Combination therapy with BRAF plus MEK inhibitors (BRAFi+MEKi) has transformed the treatment landscape and improved the clinical outcomes of patients with melanoma harboring BRAFv600 mutations." (PMID 32580351, 2020). "Since targeting BRAF in melanoma patients proved unsuccessful in the long term, the combined use of BRAF inhibitors with other therapeutic strategies (i.e., immunotherapy, standard chemotherapy or BH3-mimetics) is currently being studied." (PMID 33396645, 2020). "We conducted a retrospective analysis of data obtained from 53 melanoma patients with CNS involvement who underwent resection of their BMM tumors and for whom the BRAF mutation status was available." (PMID 32313236, 2020). "PDX models indicate that dual inhibition of BRAF and FAK inhibits ERK/MAPK re-activation in the tumor stroma, which facilitates the efficient therapeutic control of BRAF-mutant melanoma." (PMID 32546182, 2020). "In this review, we describe the clinical results of using BRAF inhibitors in advanced melanoma, with a keen interest in strategies aimed at overcoming resistance." (PMID 33419275, 2020). "Glutamine is used as another important energetic fuel in many cancer cells, and cases of glutamine addiction have already been described in melanoma with resistance to BRAF inhibitors." (PMID 32455924, 2020). "Radiation upregulated B7-H3 and CSPG4 expression on BRAF wild type human MV3 melanoma cells treated with a BRAF inhibitor." (PMID 32894202, 2020). "Other groups have demonstrated that gamitrinib enhanced the efficacy of BRAF-inhibitors in model systems of melanoma in part by the ability of gamitrinib to dampen tumor cell respiration." (PMID 32664214, 2020). "Analysis of sequential biopsies from a patient with melanoma found a transient increase in T-cell infiltrate (followed by a decrease) during BRAF inhibitor monotherapy, which increased again and persisted after a dose of anti-CTLA4 antibody." (PMID 32645969, 2020). "This study also showed that the depletion of SOX10 sensitized BRAF-mutant melanoma cells to BRAF inhibitors." (PMID 33024276, 2020). "Recently, it was also demonstrated that ALK in the exosomes secreted by BRAF inhibitor-resistant melanoma cells transferred drug resistance through activation of the MAPK signaling pathway in recipient cells." (PMID 32379831, 2020). "So, there were 11 BRAF melanomas (11/39, 28.2%, 6 primary lesions; 5 metastatic lesions) from 8 patients." (PMID 32083130, 2020). "Mutations in the BRAF, NRAS, and C-KIT genes have been associated with the histopathological characteristics of melanoma." (PMID 32775409, 2020). "Given that BRAF accounts for 95% of all RAF mutations, it also restricts the use of sorafenib in melanoma." (PMID 32476297, 2020). "For in vitro study we used three model human melanoma cells lines, i.e., A375 (homozygous BRAF V600E), G361 (heterozygous BRAF V600E), and SKMEL1 (heterozygous BRAF V600E)." (PMID 32555626, 2020). "A total of 97 patients (40 females and 57 males, overall median age 55 years) with advanced melanoma treated with BRAF inhibitors in monotherapy (41.2%) or in combination with MEK inhibitors (58.8%) were included in the analysis." (PMID 32290374, 2020).
melanoma (continued). "Case 1 In January 2012, a 69-year-old woman was diagnosed with BRAF-wild-type melanoma on the upper left leg." (PMID 32350591, 2020). "This systematic review investigated the literature on acquired v-raf murine sarcoma viral oncogene homolog B1 (BRAF) inhibitor resistance in patients with melanoma." (PMID 33003483, 2020). "Haass also demonstrated that FUCCI-red-expressing melanoma cells in G0/G1 phase survived an MEK inhibitor or a BRAF inhibitor." (PMID 32957652, 2020). "Moreover, the V600E BRAF mutation concerns a number of patients, about 50% of melanomas of all clinical types have mutations in the BRAF kinase, mainly the V600E BRAF mutation (70%–80% of all BRAF mutations in all cancers; the remaining 5% to 15% are BRAF V600K, V600D or V600R mutations)." (PMID 32610527, 2020). "For patients with advanced melanoma, immune checkpoint inhibitors are also actively utilized in combination with other targeted therapies, e.g., BRAF and MEK inhibitors." (PMID 32213878, 2020). "MM358X is derived from a patient harbouring a BRAF-mutant melanoma that progressed on BRAF and MEK inhibitors." (PMID 31857724, 2020). "NCT00794781 was a Phase I trial, evaluating the efficacy and safety of E6201 in patients with BRAF mutant advanced melanoma was terminated early due to futility based on response data." (PMID 32092958, 2020). "It was first synthesized in 2005 and was approved for the treatment of patients with melanoma with BRAF V600E in the United States and the European Union in August 2011 and February 2012, respectively." (PMID 32476297, 2020). "The majority of melanoma cases demonstrate oncogenic activation of the KIT—NRAS—BRAF—MEK—ERK central axis that is a major regulator of cell differentiation and proliferation." (PMID 32085741, 2020). "Another interesting observation is that in BRAF mutant melanoma cells a specific PMCA isoform (PMCA4b) is down-regulated in a BRAF/ERK-dependent manner, and the reintroduction of this isoform can reduce the migratory and metastatic activities of these cells." (PMID 32397400, 2020). "In melanoma cells, BRAFV600E causes constitutive activation of the BRAF tyrosine kinase, which phosphorylates and activates the MEK1/2 dual kinase, which in turn phosphorylates and activates its only target, the receptor tyrosine kinase ERK1/2." (PMID 32526884, 2020). "Activating mutations in BRAF and NRAS in the MAPK pathway have been identified in melanomas at frequencies of 50% and 20%, respectively." (PMID 33007949, 2020). "Following approval of the BRAF inhibitor vemurafenib by the FDA in 2011 for patients with advanced melanoma, PFS and OS rates have improved significantly." (PMID 32260561, 2020). "Concurrent administration of a BRAF inhibitor improves the activity and infiltration of melanoma-specific adoptive T cells." (PMID 32645969, 2020). "An activating mutation in BRAF, an oncogene involved in the MAPK pathway, has been reported in approximately 50% patients with melanoma." (PMID 31900168, 2020). "In recent years, targeted therapies for melanoma have been converted from conventional BRAF inhibitors to combination therapy with both MEK and BRAF inhibitors." (PMID 33031392, 2020). "Most importantly, the authors confirmed increased HGF expression in stromal cells of BRAF-mutant melanoma patients undergoing BRAF-targeted treatment in vivo, which resulted in poor prognosis and decreased response to treatments." (PMID 33036192, 2020). "The presence of a BRAFV600E mutation is a known predictive biomarker for the sensitivity of melanoma cells to BRAF and MEK inhibition." (PMID 32620799, 2020). "Univariate analysis revealed that the factors associated with PFS in advanced melanoma were risk factors, including liver metastases and baseline LDH levels, and a protective factor, BRAF V600 mutations." (PMID 33117684, 2020).
melanoma (continued). "Approximately 40–60% of melanoma is due to a mutation in the BRAF gene that promotes MEK-MAPK and PI3K-AKT/mTOR pathway activation and melanoma proliferation." (PMID 32178401, 2020). "To explore why BRAF-WT melanomas respond better to this combination, we examined the expression of various BCL2 family members." (PMID 32764384, 2020). "In summary, BRAF-mutant melanomas have a tumour microenvironment involving upregulation of the MAPK signalling pathway that creates a pro-tumorigenic environment and an ineffective anti-tumour immune response." (PMID 32645969, 2020). "The crucial role of BRAF-driven oncogenic ERK signaling in melanoma stimulated the preclinical and clinical development of a large number of structurally different RAF inhibitors." (PMID 32531927, 2020). "MEK inhibitors against relapsed melanomas that exhibit resistance to BRAF inhibitors can rescue melanoma antigen expression and a tumor-rejecting TME." (PMID 35310881, 2020). "Towards this goal, we developed a novel cell-based high throughput screening (HTS) assay to identify compounds that would enhance immune recognition in a BRAF mutant melanoma cell model." (PMID 32231230, 2020). "Acquired resistance to BRAF-MEK-ERK signalling inhibitors, which occurs through ERK signalling-dependent and -independent mechanisms, has been a major challenge for the treatment of BRAF-mutant melanomas." (PMID 31819183, 2020). "In melanoma, tumour growth is enhanced through activation of the MAPK pathway, which is primarily driven by activating mutations in two oncogenes: BRAF and NRAS." (PMID 33511334, 2020). "Intermitent dosing with RAF inhibitor, MEK inhibitor and ERK inhibitor (SCH772984) inhibited tumor growth in low-level BRAF amplification patient derived xenograft model of melanoma." (PMID 32092958, 2020). "In this context, our analysis of enzymatic activities of OXPHOS complexes shows upregulation of complex IV in a BRAF inhibitor-resistant melanoma cell line." (PMID 33007949, 2020). "In human BRAF V600E melanoma cell lines, JQ1 and PLX51107 treatment alone partially reduced colony growth." (PMID 31932756, 2020). "Further studies have found that in melanoma cells treated with BRAF inhibitor, the downregulation of transcription factor FOS related antigen-1 (FRA1) activates multiple signaling pathways, among which the PI3K/AKT/mTOR pathway plays a major role." (PMID 32175074, 2020). "The MAPK pathway that is activated in melanoma as a result of mutations in BRAF, NRAS, or NF1 has been shown to regulate the expression, stability, and activity of a number of different melanoma-relevant transcription factors." (PMID 33024276, 2020). "Here, we report that growth of BRAF-mutant melanoma cells is inhibited, up to complete rejection, in Siah2−/− mice." (PMID 31911617, 2020). "While in NRAS- or BRAF-mutant melanomas, there are increased levels of KIT promoter hypermethylation." (PMID 32825562, 2020). "We observed that the expression of Galectin-1 (Gal-1), a soluble ligand of Neuropilin-1 (NRP1), is upregulated in melanoma tumor samples and melanoma cells resistant to BRAF-targeted therapy." (PMID 32784465, 2020). "Both intrinsic and acquired therapy resistance remains a serious challenge for the management of BRAF(V600E)-mutant malignant melanoma." (PMID 31910904, 2020). "Although myosin II activity is controlled by BRN2-mediated downregulation of PDE5A and increased calcium signaling in BRAF mutant melanoma, our mechanism seems operative in NRAS mutant melanoma." (PMID 31935375, 2020). "POU4F1 is a stem cell-associated transcriptional factor that is highly expressed in melanoma cells and contributes to BRAF-activated malignant transformation." (PMID 32532957, 2020). "MiR-514a, a well-known key player in initiating melanocyte transformation and enhancing melanoma growth, has been reported to regulate the sensitivity of BRAF-targeted therapy by modulating the tumor suppressor NF1 gene." (PMID 32013263, 2020).